SIRT3 (sirtuin 3)
Diseases named in the same sentence as SIRT3 in open-access papers (continued):
Sharing a sentence is not in itself a finding about the gene and the disease.
cardiac hypertrophy (continued). "HKL, an activator of SIRT3, is reported to attenuate cardiac hypertrophy and kidney injury and kill cancer cells by activating SIRT3;17 however, it has not been applied for the treatment of IVDD." (PMID 30420619, 2018). "SIRT3 deacetylates/activates superoxide dismutase 2 (SOD2) which further increases the deacetylation of transcription factor forkhead box o3a (FOXO 3a) and protects against cardiac hypertrophy." (PMID 28197299, 2017). "This has been shown to reduce cellular levels of ROS, offering overall protection against stressors such as cardiac hypertrophy, where protection is lost in SIRT3 KO mice as the absence of SIRT3 leads to an increase in mitochondrial ROS accumulation during cardiac hypertrophy." (PMID 39157755, 2024). "In addition, the increased Sirt3 activities promote the expression of antioxidative enzymes such as SOD2 and catalase via the FoxO3 pathway activation, leading to the attenuation of Ang-II-induced cardiac hypertrophy via a reduction in oxidative stress." (PMID 36831262, 2023). "Therefore, SIRT3/PARP-1 pathway regulation may represent a promising tool for improving mitochondrial function and treating cardiac hypertrophy." (PMID 34776960, 2021). "Given that Sirt3 can play such a crucial role in pathological cardiac remodeling by deacetylating MnSOD, we hypothesized that LCZ696 might regulate the expression of Sirt3, mitigate oxidative stress, and thus improve cardiac hypertrophy and heart failure." (PMID 33014281, 2020). "However, the detailed information about the potential role of SIRT3 on myocardial hypertrophy by H2S in vivo was not known well." (PMID 30647820, 2018). "Importantly, the cardioprotective effects of HKL against cardiac hypertrophy were abolished in the absence of SIRT3." (PMID 30131726, 2018). "In contrast, STA is not able to reduce isoproterenol‐induced cardiac hypertrophy in SIRT3.KO mice." (PMID 28396567, 2017). "Whether or not Sirt3 has an additional direct effect upon cardiac hypertrophy independent of mPTP opening remains to be clarified." (PMID 21248376, 2011). "To test whether the interaction between SIRT3 and CypD has physiological consequences for the heart, we subjected SIRT3−/−mice to cardiac stress induced by transaortic constriction (TAC), a procedure that increases cardiac afterload and promotes cardiac hypertrophy." (PMID 21212461, 2010). "We found that NaHS failed to enhance OPA1 expression and reduce DRP1 formation in ISO-administrated SIRT3 KO mice, which may be one of the reasons that NaHS failed to improve oxidative stress and myocardial hypertrophy after ISO administration in SIRT3 KO mice." (PMID 30647820, 2018). "Our findings suggested that SIRT3 may block heart hypertrophy by inhibiting lipid metabolism disorders and may attenuate lipid accumulation in mitochondria through the deacetylation of LCAD and that the manipulation of SIRT3 expression may provide a new approach to combat hypertrophy." (PMID 25748450, 2015). "In addition, the addition of the SIRT3 inhibitor nicotinamide increased the expression levels of p-Akt and p-mTOR, which were decreased by 2-APQC, suggesting that 2-APQC may inhibit the development of myocardial hypertrophy by activating the SIRT3-regulated Akt/mTOR signaling pathway." (PMID 38744811, 2024). "Our results showed that there was no significant improvement of cardiac function, myocardial hypertrophy, fibrosis or myocardial injury in STZ-induced SIRT3-KO mice after DHY treatment." (PMID 36671063, 2023). "However, no report is available as to whether SIRT3 can interact and deacetylate PARP-1 and thereby ameliorating cardiac hypertrophy." (PMID 32139662, 2020).
breast cancer (121 papers, 2006 to 2026). A primary or metastatic malignant neoplasm involving the breast. "Genetic studies associate a variable number tandem repeat (VNTR) polymorphism (0R/0R genotype) in SIRT3 intron 5 with a significant increased breast cancer risk, implicating mitochondrial dysfunction in tumor susceptibility." (PMID 41471349, 2025). "SIRT3 overexpression inhibits glycolysis and proliferation of breast cancer cells, while SIRT3 loss increases reactive oxygen species levels to induce tumorigenesis." (PMID 39588377, 2024). "Dysregulation of SIRT3 activity has been linked to several types of cancer, including breast cancer." (PMID 38816444, 2024). "High expression of SIRT3 is associated with an unfavorable clinical prognosis of diseases such as esophageal cancer, colon cancer, stomach cancer, third degree breast cancer, oral squamous cell carcinoma, melanoma, kidney cancer, and thyroid cancer." (PMID 37175631, 2023). "In breast cancer and gastric cancer, the loss of SIRT3 promotes ROS production, leading to hypoxia-inducible factor-1α (HIF-1α) stabilization." (PMID 35832551, 2022). "1-methylbenzylamino amiodarone (MA) is another SIRT3 novel small-molecule activator that induces autophagy-associated cell death in breast cancer." (PMID 35832551, 2022). "Decreased mitochondrial SIRT3 expression is a potential molecular biomarker associated with poor outcomes in breast cancer." (PMID 33435147, 2021). "Earlier studies have shown that low Sirt3 expression is associated with reduced survival in all breast cancers and highlighted its potential role as a biomarker to assist in identifying high risk patients." (PMID 32244715, 2020). "In luminal B breast cancer, the loss of sirtuin proteins, particularly SIRT3, promotes tumorous phenotypes dictated by atypically regulated protein acetylation and thus cells are exposed to oxidative stress." (PMID 31178825, 2019). "To determine if there is a subgroup of human ER + tumors that display a loss of SIRT3/MnSOD-Ac signature, we analyzed breast cancer patient tissue microarray (TMA) slides containing all four subtypes of breast malignancies." (PMID 31160585, 2019). "Contrary to SIRT1 and SIRT2, SIRT3 is reported to have an opposing effect on angiogenesis, as loss of SIRT3 in human breast cancers, resulted in the upregulation of HIF-1α target genes like VEGF and genes involved in glycolysis." (PMID 32010617, 2019). "Until now, it has been found that SIRT3 is closely implicated in a variety of tumors, such as human oral cancer, esophageal cancer, colon cancer, liver cancer, breast cancer, melanoma, and thyroid cancer." (PMID 28947845, 2017). "The mitochondrial sirtuin 3 (SIRT3) is involved in suppressing the onset of multiple pathologies, including cardiovascular disease, fatty liver, age-related hearing loss, and breast cancer." (PMID 26928655, 2016). "Consistently, cohort study showed heterozygous loss of SIRT3 in 40% of human breast cancers formed in O2 and decreased Sirt3 expression in different types of human cancers." (PMID 27023612, 2016). "Expression of SIRT3 was reported to be significantly associated with poor prognosis in cancers such as breast cancer, colon cancer, and esophageal cancer; but opposite results were reported in hepatocellular carcinoma and gastric cancer." (PMID 27483432, 2016). "On the contrary, our results demonstrate that upregulation of SIRT3 was a risk factor for lymph node metastasis in breast cancer patients, which implicate the tumor promoter role of SIRT3 in advanced stages of breast cancer." (PMID 27483432, 2016). "Consistent with a tumor suppressor function of SIRT3 in humans, SIRT3 mRNA and protein levels are decreased in a large fraction of human breast cancers and other human malignancies, associated with deletion of the SIRT3 gene locus." (PMID 25085992, 2014).
breast cancer (continued). "However, some reports demonstrated opposite associations, linking elevated SIRT3 with prolonged survival in breast cancer or poor prognosis when downregulated in pancreatic cancers, indicating a context-dependent role of SIRT3 in tumor metabolism." (PMID 40943612, 2025). "In cultured colon cell lines, a deficiency in SIRT3 increases apoptosis, while reducing cell proliferation, invasion, and migration, whereas breast cancer cells with upregulated SIRT3 exhibit decreased glycolysis and proliferation, providing a metabolic route for tumor suppression." (PMID 41304967, 2025). "Therefore, there is a substantial negative connection between IDH2 Lys413 acetylation and breast cancer risk and SIRT3 regulates the progression of breast cancer and the metabolism of breast cancer cells by mediating IDH2 dimerization." (PMID 35571098, 2022). "The authors underlined the importance of SIRT3 as a tumor suppressor protein in breast cancer and suggest that SIRT3 may be a potential molecular biomarker for the identification of high-risk patients across all molecular subtypes of breast cancer." (PMID 33435147, 2021). "Additionally, low SIRT3 expression was associated with reduced loco-regional relapse-free survival in all breast cancer subtypes analyzed, including ER+, ER-, HER2+, and basal subtypes." (PMID 33435147, 2021). "However, some conflicting reports have shown that the high expression of SIRT3 is interrelated with positive lymph node metastasis in breast cancer and disclosed an association between the levels of SIRT3 and lymph node metastasis." (PMID 31817470, 2019). "In addition to ER+ breast cancer, low SIRT3 expression is also associated with survival in the ER−, HER2+, and basal breast cancer subtypes." (PMID 27686535, 2017). "Sirt3 deficient mice developed estrogen- and progesterone-(ER/PR−)-positive mammary tumors." (PMID 27023612, 2016). "In support of a tumor suppressor function for SIRT3, it has also been reported previously that SIRT3−/− cells displayed elevated ability to form tumors in a xenograft model and loss of SIRT3 has been identified as a frequent event in breast cancer cases." (PMID 23230084, 2012). "Moreover, SIRT3 deficiency in over one-year old mice resulted in development of estrogen- and progesterone-positive mammary tumors." (PMID 23272146, 2012). "As SIRT3 has been implicated to possess tumor suppressor function, this result suggests that loss of SIRT3 may lead to elevated Skp2 expression in breast cancers." (PMID 23230084, 2012). "SIRT3 has been observed to be abnormally elevated in TAM-resistant breast cancer cells, contributing to tamoxifen resistance by modulating estrogen receptor Erβ activity." (PMID 40303296, 2025). "SIRT3, as a lactylation removal enzyme, suppresses immune evasion in breast cancer cells and enhances PD‐1 blockade efficacy in melanoma models." (PMID 40443721, 2025). "The small molecule was found to suppress the proliferation and migration of breast cancer cells by modulating SIRT3-mediated autophagy and mitophagy pathways, both in vitro and in vivo." (PMID 41304967, 2025). "SIRT3 overexpression reduces glycolysis metabolism in breast cancer cells by suppressing PK activity." (PMID 41148848, 2025). "SIRT3 was correlated with poor prognosis in breast cancer patients, but decreased mitochondrial expression of SIRT3 was associated with poor prognosis." (PMID 40165290, 2025). "SIRT3, one of the mitochondrial sirtuins, plays multifaceted roles in breast cancer metabolism and progression." (PMID 41471349, 2025). "Benzothiazole derivatives (7ab and 7ba) that inhibit SIRT1, SIRT2, and SIRT3 in MCF-7 breast cancer cells reduced cell proliferation with IC50 values of 11.4 μM and 9.6 μM." (PMID 41471349, 2025). "Overexpression of either SIRT3 or PGC-1α in these breast cancer cells significantly reduced lactate production and glucose consumption while increasing the NAD+/NADH ratio and decreasing ATP concentration." (PMID 40303296, 2025).
breast cancer (continued). "In human breast cancer cell lines, sirtuin 3 (SIRT3), a member of the sirtuin family, acts by indirectly destabilizing HIF1-α, thus inhibiting glycolysis." (PMID 38790264, 2024). "The purpose of this work was to find possible inhibitors of SIRT3, which would stop deacetylation and hinder the proliferation of breast cancer cells." (PMID 38816444, 2024). "SIRT3-overexpressing and silenced breast cancer cells MDA-MB-231 and human embryonic kidney HEK293 cells were grown in buffered and unbuffered media at pH 7.4 and 6.8 for different times." (PMID 38931477, 2024). "Consistently, another study on hypoxic breast cancer cells showed that Sirt3 can activate mitophagy by increasing the interaction of VDAC1 with Parkin." (PMID 39472438, 2024). "In conclusion, there are few approaches available for creating and identifying SIRT3 agonists, with the majority of research on SIRT3 agonists concentrating on breast cancer." (PMID 38773972, 2024). "SIRT3 has been proved to be a tumor suppressor gene of breast cancer cells, such as breast cancer, leukemia, and liver cancer." (PMID 39598839, 2024). "Conversely, in breast cancer, SIRT3-mediated autophagy via the 5'-adenosine monophosphate-activated protein kinase (AMPK)-related pathway suppresses cell proliferation, migration, and invasion." (PMID 38773972, 2024). "For instance, breast cancer cells display noticeably lower levels of SIRT3 expression in comparison to normal epithelium." (PMID 37175631, 2023). "Being a major component of Radix Scutellaria, Oroxylin A inhibits the binding activity of hexokinase-II (HK-II) with mitochondria in a SIRT3-dependent manner to suppress glycolysis and induce mitochondrial cytotoxicity in human breast cancer cell lines." (PMID 36831555, 2023). "Murine models that lack Sirt3 are characterized by increased malignancies that resemble human luminal B breast cancer." (PMID 35938164, 2022). "SIRT3 protects breast cancer cells from cisplatin by increasing UPRmt, suggesting that inhibition of SIRT3 is beneficial for enhancing chemotherapy sensitivity in breast cancer." (PMID 35832551, 2022). "According to a recent study, loss of SIRT3 promotes acetylation of IDH2 at lysine 413 and subsequent dimerization of IDH 2 in breast cancer cell lines." (PMID 35571098, 2022). "Suppression of Sirt3 expression in breast cancer cells, and the subsequently elevated ROS production, makes these cells more susceptible to anticancer drugs." (PMID 35938164, 2022). "Zhang and colleagues performed a structure-guided design of SIRT-3 activators and tested their activity on breast cancer." (PMID 36080416, 2022). "SIRT3 knockout mice spontaneously form mammary tumors, suggesting that SIRT3 acts as a tumor suppressor." (PMID 35571098, 2022). "Conversely, tumor growth is favored by SIRT3 ablation in several mice models, and a tumor suppressor role of SIRT3 has been reported in breast cancer, hepatocellular carcinoma, metastatic ovarian cancer and B-cell malignancies." (PMID 35393510, 2022). "By upregulating the SIRT3 level, oroxylin A promotes the dissociation of HK II from the mitochondria and hinders glycolysis in breast cancer." (PMID 35571098, 2022). "SIRT3 protein expression is considerably lower in breast cancer tissue than in normal breast epithelium, according to the Desouki team’s research." (PMID 35571098, 2022). "The mitochondrial deacetylase SIRT3 was shown to behave as a TSG in breast tissue with SIRT3–/– mice developing breast cancers, while human breast cancers have reduced SIRT3 expression." (PMID 35687133, 2022). "The authors also revealed that SIRT3 overexpression suppresses the proliferation of CAMA1 breast cancer cells in the presence of high glucose." (PMID 36291902, 2022). "Armed with these findings, several researchers have investigated the tumor-suppressive role of SIRT3 in breast cancer." (PMID 36291902, 2022).
breast cancer (continued). "Sirt3 overexpression in MDA-MB-231 human breast carcinoma cells prevented Bax accumulation induced by staurosporine." (PMID 35938164, 2022). "Beyond its role in glucose metabolism, SIRT3 has also been noted for its role to control glutamine metabolism and de novo nucleotide biosynthesis in breast cancer." (PMID 34831420, 2021). "Patient clinical data also confirmed this trend, as most breast cancer patients had significantly lower SIRT3 expression levels." (PMID 34650436, 2021). "He and his colleagues have found that SIRT3-mediated deacetylation of lysine 68 regulates stem cell reprogramming in breast cancer." (PMID 33680286, 2021). "In the present study, the inhibition of Sirt3 by luteolin or brusatol suggested that luteolin suppressed Sirt3 expression in breast cancer cells to attenuate stress adaptation and chemoresistance by reducing the expression of antioxidant enzymes." (PMID 34770867, 2021). "In breast cancer cell lines, SIRT3 is often less expressed, and the overexpression SIRT3 suppresses glycolysis and cell proliferation." (PMID 34650436, 2021). "Patients with breast cancer in the lowest quartile values of SIRT3 expression had a significantly shorter loco-regional relapse-free survival." (PMID 33435147, 2021). "Previously, we showed the tumor-suppressive role of overexpressed Sirt3 in human MCF-7 breast cancer cells, which are characterized by low Sirt3 expression." (PMID 32244715, 2020). "SIRT3 was suggested as a target in breast cancer since higher SIRT3 expression was correlated with a poorer prognosis for patients with grade III breast carcinoma." (PMID 31847543, 2020). "Our present results demonstrated that the knockdown of SIRT3 further increased the intracellular ROS and mtROS levels of breast cancer cells under glucose deprivation." (PMID 32630312, 2020). "This study provides new and interesting insights with respect to the functional role of Sirt3 in the E2-dependent breast cancers." (PMID 32244715, 2020). "The expression of SIRT3 is correlated with metastatic potential in breast cancer via its control of Src/FAK signaling." (PMID 33193750, 2020). "We have recently shown that Sirt3 has the inhibitory effect on tumorigenic properties of ERα positive breast cancer cells, particularly when combined with hyperoxic treatment." (PMID 32244715, 2020). "Our results support that SIRT3 functions with a prosurvival role through the activation of the antioxidant defense system in human breast cancer cells during glucose deprivation." (PMID 32630312, 2020). "Previous studies have suggested that SIRT3 is responsible for acetylation of HSD17B4 in breast cancer cells." (PMID 32678070, 2020). "Acetylation at Lys 228 suppresses tumor proliferation, while deacetylation by SIRT3 promotes breast cancer cell and lung cancer cell survival." (PMID 32724473, 2020). "In cultured breast cancer cells (MCF7) treated with vinblastine, a microtubule-disrupting drug, the protective effect of NAD+ on microtubule loss requires sirtuin 3 (SIRT3), a mitochondrial NAD+-dependent deacetylase." (PMID 31393939, 2019). "SIRT3 overexpression in cases of several breast cancer cell lines has been able to reverse the Warburg effect." (PMID 30538800, 2018). "SIRT3 plays a tumor suppressor role in hepatocellular carcinoma and gastric cancer, but it acts as an oncogene in breast cancer, lung cancer and bladder cancer." (PMID 30367038, 2018). "Accordingly, Sirt3-knockout mice develop mammary tumors, and in many human cancer types SIRT3 is deleted or expressed at a very low level." (PMID 30197878, 2018). "SIRT3 KO murine models are found to develop tumors with similar characteristics of human luminal B breast cancer due probably to acetylation of MnSOD." (PMID 27686535, 2017).